CASP1 (caspase 1)
Diseases named in the same sentence as CASP1 in open-access papers (continued):
Sharing a sentence is not in itself a finding about the gene and the disease.
tumor (continued). "We found that the amount of mature or processed IL-1β and caspase-1 proteins in tumor tissues of caspase-1 KO and NLRP3 KO mice were significantly decreased, compared to that of WT mice." (PMID 27786298, 2016). "Ivermectin has recently been shown to have anti-tumor properties that we hereby link to its ability to augment P2X4/P2X7/Pannexin-1 signaling and caspase-1 activation, which is also associated with cancer cells’ elevated expression of P2X4/P2X7 receptors." (PMID 26552848, 2015). "The average tumor volume per mouse in the CASP-1-KO mice was significantly higher compared with the WT group." (PMID 25268644, 2014). "Allograft tumor growth was slower in Il17a−/−, Il1r1−/−, Nlrp3−/−, and Casp1−/− mice after chemotherapy treatment, demonstrating all elements in this pathway play a part in tumor protection although the exact mechanism is unclear." (PMID 24795727, 2014). "In a recent study, it was reported that while Il1r1−/− and Casp1−/− mice developed fewer tumors and had delayed tumor incidence compared to WT mice in a chemical-induced skin cancer model, Asc−/− mice had no discernible phenotype when compared to WT animals." (PMID 24474192, 2014). "At the 12th week, inflammasome loss of function decreased leukocytes infiltration into the tumor microenvironment [ASC-KO (2.1±0.7×106) and CASP-1-KO (1.4±0.3×106)], as compared to WT mice (2.75±0.16×106)." (PMID 25268644, 2014). "By synergizing with HMGB1, released from dying tumor cells and signaling through toll-like receptor (TLR) 4, activated DC are licensed to prime an anti-tumor immune response in a caspase-1- and IL-1β-dependent manner." (PMID 24795727, 2014). "Selenium recently was reported capable of inhibiting caspase-1 activation, so as to suppress tumor angiogenesis." (PMID 23349693, 2013). "Furthermore, erlotinib 51, featuring a quinazoline moiety, acts as a pyroptotic agent by initiating the pyroptosis process in lung and various other tumor cells through the stimulation of caspase-1, caspase-4, caspase-5, and caspase-11." (PMID 39316325, 2025). "CASP1 played a role in formation of inflammasomes and activation of pro-inflammatory cytokines; it may influence immune responses and tumor cell death by regulating pyroptosis and inflammasome activity." (PMID 40535567, 2025). "On one hand, inflammasomes such as NLRP3 and AIM2 can suppress tumorigenesis by enhancing anti-tumor immunity through the activation of caspase-1 and subsequent maturation and release of pro-inflammatory cytokines like IL-1β and IL-18, which recruit and activate immune cells." (PMID 40692785, 2025). "Similarly, simvastatin 64 exerts its pyroptotic activity on tumor cells by activation of caspase-1/NLRP3 pathway." (PMID 39316325, 2025). "However, epigenetic silencing of caspase-1 can promote tumor cell growth in NSCLC, indicating a dual role depending on its regulation." (PMID 40555741, 2025). "Although traditionally associated with immune cells, growing evidence indicates that epithelial and tumor cells can also activate caspase-1 in response to genotoxic or metabolic stress, particularly in the presence of reactive oxygen species (ROS) or endoplasmic reticulum (ER) stress." (PMID 41155897, 2025). "Also, resibufogenin 62 exerts its pyroptotic activity on NSCLC tumor cells by activation of caspase-1/NLRP3." (PMID 39316325, 2025). "The correlation analysis of immune cell infiltration showed that CASP1, NLRP3, and AIM2, which showed that pyroptosis was involved in the infiltration of immune cells in the tumor microenvironment and NLRP1 exhibited high diagnostic efficacy, while PYCARD demonstrated poor diagnostic efficacy." (PMID 40026444, 2025). "The effects of caspase-1 inhibition on tumor growth, however, are context-dependent." (PMID 40141358, 2025).
tumor (continued). "In colon cancer, GSDMD is activated in tumor cells through the ROS/ caspase-1 signaling pathway." (PMID 39994107, 2025). "Cell function experiments and nude mouse tumor transplantation assays confirmed that LINC00365 could regulate the expressions of pyroptosis-related proteins such as Caspase-1, Caspase-11, NLRP3 and GSDMD." (PMID 39439418, 2024). "Pharmacological inhibition of NLRP3 inflammasome using MCC950, followed by PTX administration decreased the pro-inflammatory processes associated with anti-tumor treatment as indicated by the expression of NLRP3, caspase-1, IL-1β and IL-18, compared with PTX treatment." (PMID 39433537, 2024). "To assess whether TNBC cell lines could express activated IL-1β, we performed western blot analysis to detect cleaved caspase 1 in tumor cell lines both before and after co-culture with EBV-transformed B cells." (PMID 39801513, 2024). "In addition, bromodomain-containing 4 (BRD4) inhibition was shown to prevent cell proliferation and epithelial–mesenchymal transition (EMT) and play an anti-tumour role in RCC by activating the NF-κB–NLRP3–caspase-1 pyroptosis signalling pathway." (PMID 38103146, 2024). "Mice lacking the inflammasome adaptor protein PYCARD (ASC) and caspase-1 also displayed higher tumor prevalence compared to wild-type mice, and the increased tumor burden was associated with reduced levels of IL-1β and IL-18 at the tumor site." (PMID 38553639, 2024). "In addition, A549 tumor CM significantly enhanced the cleavage and maturation of inflammasome components caspase-1 and IL-1β and upregulated AIM2." (PMID 37449203, 2023). "When inhibiting the expression of LncRNA-XIST oncogene, it could activate NLRP3 inflammatory bodies, increase the expression of caspase-1 and IL-1β, and then induce pyroptosis of tumor cells, ultimately inhibiting the occurrence and development of NSCLC." (PMID 37194012, 2023). "In addition, it was identified that simvastatin has an anti-tumor effect by down-regulating ROS production and inducing downstream caspase-1 dependent pyroptosis in the subcutaneous transplantation tumors of HCT116 cells in BALB/c nude mice." (PMID 37974278, 2023). "In conclusion, TRAF3 maybe function as tumor suppressor by modulating the caspase-1-dependent pyroptosis signaling pathway." (PMID 37798663, 2023). "Salmonella directly infects the tumor cell and induce caspase 1 by inflammasomes and destroy them by apoptosis or regulating autophagy via AKT/mTOR pathway.Salmonella also mediates T cell and innate immune cell infiltration to tumor site which enhanced killing of Salmonella localized tumor." (PMID 38090593, 2023). "Caspase-1 inhibitor (Ac-YVAD-CMK) could effectively inhibit the tumor suppressive effect of IFI16, thus it can be speculated that the tumor suppressive effect of IFI16 may be closely related to caspase-1-mediated pyroptosis." (PMID 37081882, 2023). "Similarly, NLRP3 inflammasomes promote melanoma growth by activating caspase-1 and producing IL-1β, which leads to suppression of anti-tumor immunity generated by NK cells and T cells." (PMID 37020871, 2023). "In addition to attracting and activating immune cells and inducing inflammation, caspase-1 also promotes inflammation by promoting cell survival and metastasis to influence tumor progression." (PMID 37082731, 2023). "Moreover, the nanoinhibitor combined with heat induced pyroptosis of tumor cells by the caspase 1/GSDMD pathway." (PMID 37316830, 2023). "Similarly, Nlrp3−/− mice and Caspase-1−/− mice show less and later tumor incidence when challenged with the carcinogen, 4-nitroquinoline 1-oxide (4-NQO)." (PMID 36932407, 2023). "Consistent with the findings obtained from tumor-bearing lung tissues, NR1D1 deficiency led to increased mRNA expression of Nlrp3, Il1β, and Il18 in AM, as well as increased protein expression of NLRP3 and cleaved caspase-1 in both AM and normal lung tissues." (PMID 37524704, 2023).
tumor (continued). "Accordingly, inducing pyroptosis of NSCLC cells through the NLRP3/caspase-1/GSDMD pathway may be potential targets for inhibiting the tumor progression of NSCLC." (PMID 36467499, 2022). "Caspase-1 signaling in myeloid suppressor cells can promote T-cell independent cancer progression, but the regulation of inflammasome signaling within the highly heterogeneous myeloid population in the tumor milieu remains elusive." (PMID 36439171, 2022). "However, corylin inhibited the mRNA expression and protein levels of Ifnγ, Tnf-α, Il-6, Il-1β, Nlrp3, Asc, Pannexin, and Pro-caspase 1 in the tumor tissues of AOM/DSS-induced CAC mice." (PMID 35269806, 2022). "This was consistent with our previous findings that the protective anti-tumor effects of myeloid caspase-1 deficiency were not T cell dependent." (PMID 36439171, 2022). "Casp1 is underexpressed in a variety of tumor tissues when it acts as a tumor suppressor." (PMID 35669428, 2022). "In the context of PANC, it has been demonstrated that the inhibition or deletion of components of the NLRP3 inflammasome, such as caspase-1, decreases tumor growth and metastasis in PANC by reprogramming innate and adaptive immunity in the tumor microenvironment." (PMID 35203699, 2022). "In HNSCC, we found that CASP1 is upregulated in tumor tissues (p < .01), and it seemed to be a bad prognostic biomarker (HR > 1), indicating CASP1 might be a tumor‐promoting gene in HNSCC." (PMID 35574984, 2022). "Additionally, it is important to note that there was reduced NLRP3/caspase-1 complex activity in the transgenic tumor-bearing mice upon treatment with anti-CTLA4 in all three cohorts." (PMID 35741331, 2022). "Additionally, the administration of berberine is capable of inhibiting the growth of tumor cells and decreasing the expression of IL-1β and caspase-1." (PMID 36144625, 2022). "We confirmed that these tumor-derived caspase-1 null myeloid suppressor cells could still inhibit T cell proliferation in vitro indicating that this pathway also does not affect their myeloid-mediated T cell suppression." (PMID 36439171, 2022). "Caspase-1 overexpression was also shown to induce inflammatory programmed cell death (pyroptosis), also known as inflammatory necrosis, thus inhibiting the growth of tumor cells." (PMID 35883451, 2022). "Furthermore, the TMEM176B inhibitor BayK8644 controlled tumor growth in a Tmem176b, Casp1/11 and CD8-dependent manner." (PMID 36340035, 2022). "In addition, our results indicated that decreased Dnmt1 and Dnmt3a expression abrogates promoter CpG methylation and depresses inflammatory Casp1 and Casp11 as well as pyroptotic executor Gsdmd to transcriptionally prime Mll4−/− tumor cells for pyroptosis." (PMID 36323669, 2022). "The present study identified the presence of inflammasomes in tumor cells that direct caspase-1 for pyroptosis, which may be an important node in the association of tumorigenesis and development." (PMID 34966747, 2021). "It was found that NLRP3 inflammasome could serve as the tumor-promoting effect by the activation of caspase-1 in PCa." (PMID 34930938, 2021). "Among them, except for CASP1, other genes were all the DEGs between normal and tumour tissues." (PMID 33828074, 2021). "In the present study, NLRP3/caspase-1/GSDMD pyroptosis pathway was involved in the DDP-induced anti-tumor effect of TNBC in vitro and in vivo, providing evidence that DDP might induce pyroptosis in TNBC." (PMID 34326697, 2021). "Our data suggest that targeting the DPP4 enzyme family may be a novel and effective approach to promote anti-tumour immunity in HCC via caspase-1 activation." (PMID 34771657, 2021). "It is still unknown whether tumor cells from CRC possess a functional caspase-1/IL-18 axis that could modulate the Th1/Tc1 response." (PMID 33430344, 2021). "Further studies are needed to explore the stimuli able to activate caspase-1 in tumor cells of CRC." (PMID 33430344, 2021).
tumor (continued). "Targeting the DPP4 family may be a novel and effective approach to promote anti-tumour immunity in HCC via caspase-1 activation." (PMID 34771657, 2021). "The next step was to assess whether tumor cells possessed the enzymatic machinery essential for the cleavage of pro-IL-18 into its mature form, i.e., active caspase-1, which is tightly regulated by the inflammasomes (NLRP or NLRC)." (PMID 33430344, 2021). "Cancer cell-derived extracellular vesicles (EVs) can modify the prostate microenvironment to promote cancer proliferation and can promote the activation of the NLRP3 inflammasome and caspase-1 and IL-1β release, contributing to the maintenance of proinflammatory tumor conditions." (PMID 34064909, 2021). "More significantly, our finding revealed that DPP-4i also triggered NF-кB-dependent NLRP3 inflammasome activation, leading to caspase-1-mediated processing of IL-1β and IL-33, two critical proinflammatory cytokines for the tumor-immune-suppressive microenvironment." (PMID 34631556, 2021). "However, CASP1-mediated cell pyroptosis has also been shown to participate in various tumor development stages." (PMID 34531375, 2021). "Since the inflammasome is the key molecule that directs caspase-1 to pyroptosis, this could be a critical node in the relationship between tumor cells and pyroptosis." (PMID 34869306, 2021). "Considering the status of active caspase-1 (aCasp1) in tumor cells, two subgroups of CRC appeared." (PMID 33430344, 2021). "In order to assess whether pro-IL-18 expressed by tumor cells can be processed and secreted as a mature form, we first assessed the expression of active caspase-1, essential for the processing of IL-18." (PMID 33430344, 2021). "Thus, our findings show that the majority of CRC exhibits an activated functional caspase-1/IL-18 axis in tumor cells, and that IL-18 is able to modulate the IFNγ response of TILs in vitro." (PMID 33430344, 2021). "In addition, knockdown of NLRP3 triggered a reduction of NLRP3 and caspase-1 expression levels in excised tumor masses." (PMID 34930938, 2021). "Moreover, we performed IHC staining CD44s, E-cadherin, Vimentin, and caspase-1 in tumor tissues obtained from the corresponding group of nude mice." (PMID 33168816, 2020). "Thus, the absence of caspase-1 in the hematopoietic cell lineage is responsible for the delay in tumor growth, suggesting that caspase-1-expressing immune cells support cancer progression." (PMID 33042810, 2020). "We finally verified whether gAcrp suppresses inflammasomes activation in tumor tissues and found that gAcrp reduced the expression levels of active IL-1β and p20 caspase-1." (PMID 32155890, 2020). "In tumor ovaries, caspase-1 staining was intense throughout the section." (PMID 31923221, 2020). "In addition, in the tumor cell suspension from Caspase-1 KO mice, significantly more NK cells were activated (positive to IFN-γ) in response to YAC-1 or 4T1 stimulation compared with WT." (PMID 33042810, 2020). "Furthermore, DHA regulates the crosstalk between autophagy and IFI16/caspase-1 inflammasome, which inhibits IL-1β production in tumor microenvironment." (PMID 32577124, 2020). "In our previous murine study, we reported that tumor-associated macrophages (TAMs) populated lung tumor lesions exerting a pro-tumor activity in a caspase-11/caspase-1-dependent manner, implying that the activation of the inflammasome in TAMs was pro-tumorigenic." (PMID 33187551, 2020). "Further research found that DHA could also reduce the expression of pro-caspase-1 and inhibit the activation of caspase-1 in Hep-2 cells in vitro and IL-1β that was produced in tumor microenvironment in vivo." (PMID 32577124, 2020). "Furthermore, caspase-1 was correlated with IL1β (r = 0.74, p = 0.046) in tumor-containing hen ovaries." (PMID 31923221, 2020). "Low CASP-1 expression is correlated with tumor stage, metastasis and patient survival." (PMID 33014808, 2020).
tumor (continued). "Together, active caspase-1 cleaves gC1qR and boosts aerobic glycolysis in tumor cells." (PMID 33102234, 2020). "Additionally, the activity of caspase-1 was increased by LncRNA ADAMTS9 overexpression in mice tumor tissues." (PMID 32516127, 2020). "Moreover, flow cytometry analysis revealed augmented caspase-1 activation in resident CD11chi MHC II+ CD11b+ classical DCs (cDCs) in TDLN from Tmem176b−/− versus WT tumor-bearing mice." (PMID 31085177, 2019). "However, in pancreatic ductal adenocarcinoma, studies have demonstrated that the inhibition or deletion of NLRP3, ASC, or caspase-1 decreases tumor growth and metastasis by reprogramming innate and adaptive immunity in the tumor microenvironment." (PMID 31242947, 2019). "However, we found increased caspase-1 activation in tumor-draining lymph nodes (TDLN) from Tmem176b−/− mice compared with WT animals." (PMID 31085177, 2019). "Taken together, our results suggest that berberine may seves as a modulator of ERK1/2 signaling, responsible for both tumor cell death and inactivation of caspase-1-mediated signaling." (PMID 31139563, 2019). "Thus, Tmem176b deletion enhances CTL-mediated tumor control through mechanisms involving the caspase-1/IL-1β pathway." (PMID 31085177, 2019). "Caspase-1 can activate the pro-inflammatory cytokines IL-1β and IL-18, and promote inflammation and the formation of the tumor microenvironment, thus potentially promoting tumor infiltration and metastasis." (PMID 29626935, 2018). "In addition, EO771 cancer cells were orthotopically implanted in WT or caspase-1−/− mice, tumor growth was significantly impaired in caspase-1−/− mice." (PMID 28974683, 2017). "Caspase-1 cleaves and activates the proinflammatory cytokines IL-1β and IL-18 into their mature peptides, which contribute to the down-stream inflammatory response and formation of tumor microenviroment." (PMID 28424426, 2017). "Furthermore, the administration of caspase-1 inhibitors or the infusion of bone marrow-derived macrophages genetically engineered to overexpress murine MCAD markedly suppresses tumor growth." (PMID 28974683, 2017). "Researches have confirmed that chemotherapy drugs could induce the production of NLRP3 inflammasome, activate the caspase-1 molecules and induce secretion of IL-1β, which can inhibit the anti-tumor effect of chemotherapy." (PMID 29312552, 2017). "Similarly, in primary TAMs derived from MMTV-PyMT mouse tumor tissues, the caspase-1 inhibitor YVAD inhibited PPARγ cleavage." (PMID 28974683, 2017). "Overall, our study uncovers a novel mechanism of G9A promoting tumor cell growth and invasion by silencing CASP1, and implies that G9A may serve as a therapeutic target in treating NSCLC." (PMID 28383547, 2017). "Moreover, to rule out the possibility that treatment with inhibitors directly impacts tumor cells, caspase-1 knockdown THP-1 cells were constructed, and these experiments were repeated and the similar results were observed." (PMID 28974683, 2017). "Results from hierarchy clustering and linear regression analyses showed that the expression of tumor-associated ASC and IL-18 are closer to ALDH1 expression, NLRP3 and Caspase-1 are close to ALDH1 expression, and NLRP3, Caspase-1, ASC, and IL-18 are close to CD44 and BMI1 expression." (PMID 28865486, 2017). "Overall, our results identify a novel mechanism by which G9A enhances tumor cell proliferation and invasion by silencing CASP1 expression, and suggests that G9A may serve as a therapeutic target in NSCLC." (PMID 28383547, 2017). "We next investigated whether PsV could directly induce intestinal tumour cell death via activating caspase-1." (PMID 28397782, 2017). "Our study also indicates that CASP1 suppresses tumor cell invasion and migration in NSCLC cells." (PMID 28383547, 2017).